APC (APC regulator of Wnt signaling pathway)
Diseases named in the same sentence as APC in open-access papers (continued):
Sharing a sentence is not in itself a finding about the gene and the disease.
Familial adenomatous polyposis (continued). "In particular, the APC tumor suppressor gene, a key component of the WNT cascade, has been identified as the cause of familial adenomatous polyposis (FAP)." (PMID 38049863, 2023). "Heterozygous mutations in APC represent the earliest event in sporadic colorectal carcinogenesis (CRC) onset and cause familial adenomatous polyposis syndrome (FAP), a heritable disease that increases the risk of colon cancer development." (PMID 34486752, 2022). "Germline inactivation of the APC gene can result in the formation of hundreds of colonic polyps, a condition known as familial adenomatous polyposis (FAP)." (PMID 35267592, 2022). "For many patients, including those with precursor familial adenomatous polyposis condition (FAP), CRC begins with germline or somatic mutations in the tumor-suppressor, adenomatous polyposis coli (APC) gene." (PMID 35669174, 2022). "For the investigation of somatic APC variants, previously published results on sporadic adenomas (HGCA) were examined, and available in-house sequencing data generated from adenomas obtained from patients with unexplained colorectal adenomatous polyposis were re-analysed." (PMID 34843512, 2021). "In contrast, in APC-mutant tissues from familial adenomatous polyposis (FAP) patients, the proportion of ALDH+ SCs progressively increased while NECs markedly decreased." (PMID 33112876, 2020). "However, it has been documented that adenomatous polyposis coli (APC) germline mutations cause aneuploidy and are responsible for familial adenomatous polyposis (FAP), while higher polo-like kinase 1 (PLK1) gene expression can increase the survival for colon cancer patient with a truncated APC." (PMID 31263147, 2019). "Familial adenomatous polyposis (FAP), characterized by an ultra-high risk of CRC, is a rare genetic disease usually caused by a pathological mutation of the APC gene in the germ line." (PMID 31567943, 2019). "APC is one of the key genes in the initiation of polyp formation in both familial adenomatous polyposis (FAP) and FAP-like sporadic CRCs." (PMID 31080553, 2019). "APC mutations are also responsible for a hereditary predisposition to CRC, familial adenomatous polyposis (FAP)." (PMID 29419487, 2018). "Various genes (RUNX2, PLOD, EVC, GLA, APC, NEMO) have been associated with supernumerary teeth formation in several syndromes, such as Cleidocranial dysplasia, Ehlers-Danlos Type IV, Ellis-Van Creveld, Fabry disease, Familial adenomatous polyposis, and Incontinentia pigmenti." (PMID 30148467, 2018). "The inactivation of APC is found in about 85% of sporadic CRC and is mutated in the germline of patients with FAP (Familial Adenomatous Polyposis)." (PMID 28573140, 2017). "The cell-protective properties of APC are particularly well characterized in the hereditary polyp syndrome known as familial adenomatous polyposis (FAP)." (PMID 27144584, 2016). "Using next-generation sequencing (NGS) to analyze a patient with sporadic familial adenomatous polyposis in whom no APC mutations were found by Sanger sequencing, we identified a novel APC mosaicism at a spliced donor site (c.834+2 T>C) in his leukocytes, normal colonic mucosa and adenoma." (PMID 27081559, 2015). "Familial adenomatous polyposis (FAP) is the second most common hereditary CRC syndrome and is caused by a germline mutation in the APC gene (MIM *611731)." (PMID 25860647, 2015).
Familial adenomatous polyposis (continued). "A “key” initial mutation is the early mutation of the adenomatous polyposis coli (APC) tumor suppressor gene, involved in both sporadic CIN and, when germline mutated, in all Familial Adenomatous Polyposis (FAP)." (PMID 23965959, 2013). "Among the components of the Wnt/β-catenin pathway, the APC gene is known to be the primary target in patients with familial adenomatous polyposis (FAP) colon cancers." (PMID 21966251, 2011). "The clinical manifestations of MAP resemble familial adenomatous polyposis (FAP; MIM#175100), which is caused by autosomal dominantly inherited pathogenic variants in the APC gene." (PMID 21962078, 2011). "One common genetic model that has been employed is the APC min mouse because it is a closely mimics human familial adenomatous polyposis (FAP), a condition in which multiple polyps develop in the colon." (PMID 27713339, 2010). "The primary tumour predisposition in familial adenomatous polyposis (FAP) and MAP is to colorectal adenomas via APC mutation." (PMID 17505512, 2007). "CMTC, which was a subtype of PTC in the WHO 4th, is related to familial adenomatous polyposis (FAP) and genetic abnormalities in the β-catenin system such as APC." (PMID 38672067, 2024). "Mutations in the APC gene have been reported in approximately 80% of all sporadic non-hypermutated CRC, 50% of sporadic hypermutated CRC, and familial adenomatous polyposis (FAP) cases." (PMID 38182897, 2024). "These include APC for familial adenomatous polyposis (FAP); BMPR1A and SMAD4 for Juvenile Polyposis Syndrome (JPS); MUTYH for MUTYH-associated polyposis; PTEN for PTEN tumor/hamartoma syndrome (or Cowden syndrome/Bannayan–Riley–Ruvalcaba syndrome); and STK11 for Peutz–Jeghers syndrome." (PMID 37965459, 2023). "Genetic testing of the APC gene by sequencing analysis and MLPA is available across commercial laboratories for the definitive genetic diagnosis of familial adenomatous polyposis (FAP)." (PMID 37601671, 2023). "On the other hand, only 5% of CRC cases are due to a hereditary predisposing syndrome, the most frequent being Lynch Syndrome (LS) and Familial Adenomatous Polyposis (FAP), characterized by loss of function of mismatch repair genes (MMR) and APC (WNT pathway), respectively." (PMID 36005154, 2022). "The tumor suppressor gene APC is mutated in the majority of sporadic CRC cases in humans, and a germ line mutation in APC leads to a hereditary tumor syndrome known as familial adenomatous polyposis (FAP)." (PMID 35587635, 2022). "One example is familial adenomatous polyposis (FAP), a disease where the tumor suppressor gene APC is mutated and β-catenin can no longer be degraded." (PMID 36612190, 2022). "APC mutations can be detected both in familial adenomatous polyposis (FAP) and non-FAP tumors including HNPCC and sporadic colorectal cancer." (PMID 34489406, 2021). "Those mutations can be in the tumor suppressor gene APC on chromosome 5q as in familial adenomatous polyposis (FAP) or mutated DNA mismatch repair genes in hereditary non-polyposis colorectal cancer (HNPCC)." (PMID 34836311, 2021). "In the adenomatous polyposis coli (APC) animal model of human familial adenomatous polyposis (FAP), mice develop numerous polyps in the intestinal tract due to a truncation in the APC gene." (PMID 32674255, 2020). "The purpose of this study was to determine sequence variants of the APC gene in patients with familial adenomatous polyposis (FAP) phenotype and positive or negative family history." (PMID 31547110, 2019). "Compared with adjacent normal tissues, tumor samples exhibited hypermethylation of Estrogen Receptor 1, Cadherin 13, Retinoic Acid Receptor Beta, Cell Surface Adhesion Molecule, and Adenomatous Polyposis Coli (ESR1, CDH13, RARB, IGSF4, and APC) genes." (PMID 31390840, 2019).
Familial adenomatous polyposis (continued). "The WNT pathway is most famously known for its involvement in hereditary familial adenomatous polyposis (FAP), where a mutated APC tumor suppressor gene fails to regulate β-catenin regulation, allowing tumor cells to progress towards malignancy." (PMID 31382613, 2019). "Of the familial forms of CRC, familial adenomatous polyposis (FAP; associated with germ line mutations in genes such as APC) and hereditary non-polyposis colon cancer (HNPCC; associated with DNA mismatch repair enzymes) are the most common." (PMID 26959117, 2016). "Finally, we applied hapLOHseq to WES experiments on two adenomas from a patient with familial adenomatous polyposis (FAP), a cancer syndrome resulting from a germline mutation in APC (5q), where the acquired second somatic mutation (or ‘hit’; Knudson, 1971) may be an LOH event." (PMID 27288500, 2016). "Moreover, heritable changes in the APC gene frequently lead to familial adenomatous polyposis (FAP)." (PMID 25076949, 2014). "De Rosa and colleagues examined a cohort of 24 patients suffering from familial adenomatous polyposis (FAP), each with a germline mutation in the APC gene, comparing them to 17 FAP patients without apparent APC mutations and 9 controls." (PMID 24101931, 2013). "For instance, it is not clear how a germline APC mutation can initiate intestinal tumors as it clearly does in ApcMin/+ mice and familial adenomatous polyposis (FAP) patients." (PMID 24224156, 2013). "Sulindac, a well-known chemopreventive drug used in adenomatous familial polyposis (AFP), inhibited tumour growth in APC mutant mice but increased tumour appearance in MLH1 mutant mice." (PMID 22649288, 2012). "This also occurs in adenomas derived from familial adenomatous polyposis (FAP) patients, therefore APC mutations do not confer resistance to cell death in response to loss of cell-cell contacts." (PMID 9083330, 1997). "Carriers of this variant do not exhibit clinical features of Familial adenomatous polyposis (FAP), distinguishing it from higher penetrance APC variants." (PMID 40970488, 2025). "One prominent example for such common and clinically oriented nomenclature is the term Familial Adenomatous Polyposis (FAP), which has not been substituted (yet) by the gene-based term “APC-related polyposis” or even “APC-related cancer predisposition syndrome”." (PMID 41210224, 2025). "Targeted mutational screening of the APC and MYH was performed on blood samples and digestive tract biopsies; gene panels for familial adenomatous polyposis and ES were negative." (PMID 36926521, 2023). "Unlike sporadic desmoid tumors, familial adenomatous polyposis associated desmoid tumors result from mutations in both the wild-type CTNNB1 and adenomatous polyposis coli (APC) genes." (PMID 36983801, 2023). "Familial adenomatous polyposis (FAP) is an autosomal dominant syndrome, caused by mutation in the adenomatous polyposis coli (APC) gene, leading to a lack of degradation of β-catenin in the cytoplasm, which then enters the nucleus and enhances the transcription of oncogenes." (PMID 36553450, 2022). "From 88 patients with suspected familial adenomatous polyposis, 25 unrelated APC negative polyposis patients were identified." (PMID 33628596, 2021). "However, in familial adenomatous polyposis (FAP) patients and in mouse models of APC inactivation, the rate of increase is modest and variable." (PMID 31792216, 2019).
Familial adenomatous polyposis (continued). "Although this patient did not have a history of familial adenomatous polyposis, functional analysis suggested the R1835G mutant APC showed attenuated repression of Wnt/β-catenin signaling activity." (PMID 29535845, 2018). "Only one case has been reported of a germline truncating mutation of the APC gene, a 5-bp deletion at the β-catenin binding site in an individual with familial adenomatous polyposis (FAP); LOH of the APC gene in pancreatoblastoma was also observed in this case." (PMID 29535845, 2018). "Ectopic expression of APC, but not its familial adenomatous polyposis-related truncation mutant, prominently enhances HIV-1 production." (PMID 28134256, 2017). "NMNU = n-methyl-N-nitrosourea, AOM = azoxymethane, DMH = 1,2-dimethylhydrazine, APC = adenomatous polyposis coli, NA = not measured." (PMID 27713339, 2010). "However, it also appears to play a role in maintaining normal GI microbiota and has recently been suggested as a candidate gene for APC-negative familial polyposis." (PMID 39057027, 2024). "APC is a tumour-suppressor protein and its loss-of-function mutations have been demonstrated to result in the over-activation of WNT/β-catenin signalling, and familial adenomatous polyposis syndrome with or without supernumerary tooth formation." (PMID 36901686, 2023). "Certainly, APC and MUTYH are not the only genes predisposing to the familial polyposis." (PMID 29954149, 2018). "In the absence of APC, Wnt gene is illustrated by the autosomal dominant condition, familial adenomatous polyposis (FAP), in which hundreds to thousands of adenomatous colonic polyps develop, leading to almost 100% lifetime risk of developing CRC in the absence of pre-emptive colectomy." (PMID 25713610, 2014). "APC loss-of-function mutations are associated with the over-activation of WNT/β-catenin signalling and subsequent familial adenomatous polyposis (FAP; MIM 175100) with or without multiple supernumerary teeth." (PMID 36901686, 2023). "Previous studies have documented abnormalities in the adenomatous polyposis coli (APC) gene at chromosome 5q22 to result in familial adenomatous polyposis (FAP), hereditary non-polyposis colon cancer and other cancers." (PMID 25210923, 2014). "Recently, colonic organoids derived from patients with familial adenomatous polyposis (FAP) were used to test potential anticancer activity of XAV939, rapamycin and geneticin, and it was seen that geneticin specifically inhibited the growth of APC-mutant FAP-colonic organoids." (PMID 33977021, 2021). "The genetic risk of CRC is associated with rare but high-penetrance germline mutations in susceptibility genes, such as MLH1 and APC, that cause hereditary nonpolyposis colorectal cancer (HNPCC, also known as Lynch syndrome) and familial adenomatous polyposis (FAP), respectively." (PMID 32722560, 2020). "Familial adenomatous polyposis (FAP) and hereditary nonpolyposis colorectal cancer (HNPCC) are autosomal dominant diseases that result from inherited genetic mutations in adenomatous polyposis coli (APC) and mismatch repair genes." (PMID 22496728, 2012).
colon carcinoma (647 papers, 2001 to 2026). "Our study underscores the critical role of germline APC mutations in colon cancer initiation, revealing how specific mutations influence disease severity." (PMID 40695959, 2025). "For these experiments, we utilized the established genetically engineered KPC:APC model in which conditional mutant alleles predispose mice to the development of colonic tumors following treatment with tamoxifen." (PMID 39941740, 2025). "A single germline mutation in the APC gene, although insufficient for complete tumorigenesis, predisposes individuals to colon cancer by initiating early events associated with uncontrolled cellular proliferation." (PMID 40695959, 2025). "Although phosphorylation of β‐catenin is blocked via multiple mechanisms in colon cancer, such as APC truncation and AXIN2 mutation, we found that CRC cell lines, such as MC38, CT26, and Caco‐2 cells exhibit phosphorylated β‐catenin." (PMID 40884233, 2025). "For example, in colon cancers associated with adenomatous polyposis coli (APC) deletion, increases in protein synthesis occur through activation of translation elongation and not initiation, mediated by increased eEF2 activity." (PMID 41390489, 2025). "APC deletions/mutations are involved in the aberrant activation of Wnt/β-Catenin signaling in about 80% of sporadic colon cancers." (PMID 40558481, 2025). "Mutations in APC, found in ~80% of colon cancer, enhance β-catenin stabilization and induce colonic tumorigenesis." (PMID 40399276, 2025). "Most recently, studies have shown that differentiated Paneth cells, upon inflammatory‐associated APC loss or targeted mutation of APC, initiate tumour formation in patients with inflammatory bowel disease and in sporadic colon cancer." (PMID 40212011, 2025). "Since Na,K-ATPase was accumulated in regions of potential lysosomal localization, we used SW480 colon cancer cells with constitutive Wnt signaling resulting from a mutation of adenopolyposis coli (APC) that had elevated levels of lysosomes." (PMID 38713004, 2024). "It has been discovered that half of all human colon tumors with an intact APC protein have a mutation in the β-catenin gene." (PMID 39339648, 2024). "One of the first tumour driver mutations in colon cancer occurs in the adenomatous polyposis coli (APC) gene." (PMID 38635059, 2024). "The identification of APC mutations in colon cancer pathogenesis back in 1991 provided the initial evidence for the involvement of Wnt/β-catenin signaling in tumorigenesis." (PMID 38886806, 2024). "We show that eIF3a expression is upregulated in human colon cancer tissues, pre-cancerous adenoma polyps, and associates with β-catenin level and APC mutation in human samples, and that eIF3a overexpression transforms intestinal epithelial cells." (PMID 39413959, 2024). "We note that a recent study describes a largely balanced chromothripsis event involving the APC locus as a germline cause of a colon cancer predisposition." (PMID 38776926, 2024). "To functionally address the role of Bcl11b in tumor formation, we deleted Bcl11b in LoVo cells, a colon cancer cell line carrying APC mutation." (PMID 39433900, 2024).